IGFBP1 (insulin like growth factor binding protein 1)
Diseases named in the same sentence as IGFBP1 in open-access papers (continued):
Sharing a sentence is not in itself a finding about the gene and the disease.
Insulin resistance (continued). "Interestingly, the genes with the second and third highest FC in this study, namely IGFBP1 (log2FC = 11.29) and ITIH1 (log2FC = 11.20), respectively, were also associated with insulin resistance." (PMID 37889672, 2023). "Levels of IGFBP-1 have been perceived as an expression of the degree of insulin resistance." (PMID 37443807, 2023). "A study reported that clomiphene increases insulin-like growth factor binding protein-1 and reduces insulin-like growth factor-I but does not correct insulin resistance associated with women with polycystic ovarian syndrome." (PMID 36290602, 2022). "The reduction in insulin resistance after metformin treatment is associated with an increase in plasma insulin-like growth factor-binding protein 1 (IGFBP-1) concentrations and a decrease in the insulin-like growth factor (IGF-I)/IGFBP-1 ratio." (PMID 35267644, 2022). "Indeed, reductions in circulating IGFBP-1 are often attributed to the inhibitory effects of hyperinsulinaemia on hepatic IGFBP-1 expression, prior to the development of hepatic insulin resistance." (PMID 33758952, 2021). "Hence, inflammatory markers and IGFBP-1 phosphoisoforms seem to indicate obesity related insulin resistance." (PMID 32652973, 2020). "Finally, IGFBP-1 displays promise for therapeutic angiogenesis, as a pro-angiogenic protein with ability to increase perfusion in tissue ischemia in the setting of insulin resistance." (PMID 32190801, 2020). "The aim here was to study in overweight and obese women, typically manifesting with insulin resistance, whether IGFBP-1 and MMP-8 are related to and reflect systemic low-grade inflammation, metabolism and diet." (PMID 32923723, 2020). "The low serum levels of IGFBP-1 in PCOS women led to the hypothesis that insulin resistance in PCOS inhibits the production of IGFBP-1 which in turn stimulates excess androgen production in PCOS." (PMID 30775682, 2018). "Low levels of IGFBP-1 were detected in all insulin resistance women." (PMID 30775682, 2018). "Hepatic insulin resistance was considered for IGFBP-1 level quartiles 1 to 3 (<6.67 ng/ml)." (PMID 25411786, 2014). "IGFBP-1 may act as a measure of hepatic insulin resistance as well as whole body insulin resistance." (PMID 25461385, 2014). "Patients with insulin receptor defects also differ biochemically from other types of insulin resistance by displaying elevated adiponectin, IGFBP1, and SHBG, which are all commonly suppressed in common insulin resistance or lipodystrophy-associated severe insulin resistance." (PMID 23766565, 2013). "Adiponectin, SHBG- and IGFBP1 are all commonly reduced in people with obesity-related insulin resistance and various lipodystrophies, so these markers are helpful diagnostically in distinguishing those with insulin receptor dysfunction from those with other causes of severe insulin resistance." (PMID 23766565, 2013). "Patients with INSR mutation differ biochemically from patients with more common insulin resistance associated with the metabolic syndrome by having high levels of adiponectin, sex-hormone-binding globulin (SHBG), and insulin-like growth factor-binding protein 1 (IGFBP1)." (PMID 23766565, 2013). "Adiponectin may be a more useful marker than IGFBP-1 and triglyceride for monitoring insulin resistance in SGA children with catch-up growth." (PMID 23186039, 2012). "Our findings indicated that adiponectin might be a more effective marker than IGFBP-1 and triglyceride for monitoring insulin resistance in SGA children with catch-up growth." (PMID 23186039, 2012). "Insulin resistance and impaired glucose tolerance are observed in IGFBP-1 transgenic mice." (PMID 23186039, 2012). "IGFBP1 may also be a marker for insulin resistance and be involved in the development of type 2 diabetes." (PMID 22007308, 2011).
Insulin resistance (continued). "The mechanism by which insulin resistance contributes to abortion is unclear, but it may involve the suppression of glycodelin and insulin-like growth factor-binding protein-1 (IGFBP-1) production in the endometrium, leading to an unfavorable environment for implantation." (PMID 40944084, 2025). "In obesity, hyperinsulinemia caused by insulin resistance leads to reduced growth hormone secretion, but IGF-I levels remain stable due to increased hepatic GH sensitivity, with suppressed IGFBP-1 levels in response to elevated insulin, which may decreasing the protection toward bladder cancer." (PMID 39723162, 2024). "Finally, IGFBP1 is negatively associated with impaired glucose tolerance and obesity and serves as a marker of HIS, while IGFBP3 correlates directly with hepatic insulin resistance and diabetes incidence." (PMID 36959287, 2023). "In people with diabetes, low levels of IGFBP-1 predicted future cardiovascular risk, and in a prospective study of non-diabetics at baseline, high levels of IGFBP-1 reduced the risk of developing insulin resistance or type 2 diabetes during a 10-year time span." (PMID 37298072, 2023). "Mechanistically, higher adiposity increases the concentration of circulating pro-inflammatory markers which may lead to insulin resistance, simultaneously decreasing the levels of insulin-like growth factor binding-protein 1 (IGFBP-1) and increasing the bioavailability of IGF-1." (PMID 33375174, 2020). "However, we have presented the presence of four different SGA populations compared to normal controls in the exploration of system-wide adiponectin, IGFBP-1, triglyceride levels and insulin resistance in SGA children, while considering height and fat catch-up growth." (PMID 23186039, 2012). "Therefore, insulin resistance in patients with PCOS might inhibit the production of IGFBP1." (PMID 36072434, 2022). "Potentially, low IGFBP-1 levels enable the development of T2DM, but as T2DM develops, IGFBP-1 concentrations rise as a consequence of hepatic insulin resistance." (PMID 30392760, 2019). "This study aims to analyze the correlation between the levels of IGFBP-1 and HOMA-IR in insulin resistance PCOS." (PMID 30775682, 2018). "The study is aimed to analyze the correlation between the levels of IGFBP-1 and HOMA-IR on insulin resistance in PCOS." (PMID 30775682, 2018). "To further confirm that insulin resistance was relieved in these cells, we examined the expression of genes involved in insulin resistance (INSR, CREB, CRTC, IGFBP-1, and GLUT2)." (PMID 26077338, 2015). "We then analyzed the correlations between serum IGFBP-7 protein levels and other laboratory variables, including fasting glucose, fasting insulin, homeostasis model of assessment insulin resistance (HOMA-IR), IGF-1, and IGFBP-1." (PMID 24180466, 2013). "Other top predictors included markers of insulin resistance and the IGF pathway (insulin, IGFBP1, uric acid), sex hormones (free estradiol, SHBG), lipid-soluble micronutrients (vitamin D3, lycopene, CoQ10, alpha-tocopherol) and markers of inflammation (CRP)." (PMID 22912885, 2012). "We also examined the relationship between insulin, C-peptide, IGFBP-1, and obesity (BMI or waist-hip ratio (WHR), which are factors related to colorectal adenomas, CRC and insulin resistance." (PMID 22950808, 2012). "Insulin resistance stimulates the hepatic synthesis of insulin-growth factor 1 (IGF-1) and increases its bioactivity by reducing insulin-growth factor binding protein 1 (IGFBP-1) and 2 (IGFBP-2) levels." (PMID 39199391, 2024). "This is consistent with low IGFBP1 levels reflecting insulin resistance and hepatic steatosis in nonpregnant adults and children." (PMID 38627562, 2024). "Moreover, when considering insulin resistance in PCOS, further evaluation on the interaction between IGFBP-1 and IGF-1 is required for a better understanding of the pathophysiology." (PMID 30775682, 2018).
Insulin resistance (continued). "Consequently, variables such as glucose, homeostasis model assessment-insulin resistance (HOMA-IR), IGFBP-1 and hemoglobin A1c (HbA1c) in the maternal circulation are of potential interest in relation to offspring size and body composition." (PMID 26184296, 2015). "The down-regulated expression of GCK and up-regulated expression of IGFBP1, PPARGC1A and SLC2A4 may indicate obesity and insulin resistance in rhesus models of liver steatosis." (PMID 26442469, 2015). "Peripheral insulin resistance in subjects born SGA at term has been described in both children and adults, and in our children born SGA at term, we have recently reported elevated insulin and HOMA-IR values and a tendency to lower IGFBP1 after BMI adjustment." (PMID 23781317, 2013). "Further, the onset of DM and IGT is characterized by insulin resistance, hyperinsulinemia, insulin stimulation of IGF-I production in the liver through the upregulated GH signaling pathway (e.g., upregulated expression of the hepatic GH receptor), and decreased IGFBP-1 level." (PMID 34239560, 2021). "On the basis that a positive effect of IGFBP-1 on endothelial repair is only observed in insulin-resistant and not insulin-sensitive mice, we next investigated whether IGFBP-1 modulates angiogenesis in the setting of insulin resistance." (PMID 32190801, 2020). "As IGF-I promotes insulin sensitivity, this increase in circulating IGF-I may compensate for the lack of IGFBP-1 and explain why IGFBP-1-KO do not display impaired glucose tolerance or insulin resistance in line with population data in the literature." (PMID 32190801, 2020). "In addition, low IGFBP-1 and IGFBP-2 coupled with elevated IGF-1, may represent compensatory mechanisms in response to increasing insulin resistance." (PMID 29351335, 2018). "The reciprocal negative association of IGFBP-1 and HOMA-IR may represent a strong interaction of the physiological processes of both whole-body and hepatic insulin resistance." (PMID 25411786, 2014). "Impaired IGFBP-1 suppression in response to an oral glucose load is also a predictor, and may indicate hepatic insulin resistance; however it is not a better marker than the fasting concentrations." (PMID 26237614, 2014). "In fact, serum concentration of IGFBP‐1, unlike IGFBP‐3 which binds 75–90% of circulating IGF‐I, is heavily influenced by the metabolic (i.e., insulin resistance, and insulin and glucagon levels) and nutritional (fasting and refeeding) state of the individual." (PMID 26443692, 2016).
Hyperinsulinemia (79 papers, 2005 to 2026). An increased concentration of insulin in the blood. "Hyperinsulinemia can also decrease the production of insulin-like growth factor-binding protein 1 (IGFBP-1) in the liver and other organs and is linked to lower plasma insulin-like growth factor binding protein-2 (IGFBP-2) levels." (PMID 35270737, 2022). "At the same time, there is no strong correlation between the IGFBP-1 deficiency and the severity of hyperinsulinemia and IR, which suggests the presence of additional mechanisms mediating the inhibition of IGFBP-1 production in PCOS." (PMID 33429918, 2021). "Hyperinsulinemia and low IGFBP-1 are also associated with increased likelihood of developing cardiovascular disease." (PMID 23840881, 2013). "Low serum IGFBP-1 levels are associated with hyperinsulinemia and subsequently with overweight or obesity." (PMID 24246027, 2013). "Reduced serum IGFBP-1 levels are considered to reflect hyperinsulinemia and cardiovascular risk in adults and obese children." (PMID 23186039, 2012). "There is a correlation between low levels of IGFBP-1 and hyperinsulinemia, which may also be linked with increased CVD risk." (PMID 33905470, 2020). "Similarly, compensatory hyperinsulinemia is associated with reductions in insulin-like growth factor binding protein-1 (IGFBP-1), corresponding to higher cellular concentrations of free insulin-like growth factor-1 (IGF-1)." (PMID 22253996, 2010). "Hyperinsulinemia reduces insulin growth factor binding protein 1 (IGFBP-1) and glycodelin levels, affecting trophoblast proliferation and potentially hCG production." (PMID 40970032, 2025). "BC patients with high insulin levels have bad prognosis, and chronic hyperinsulinemia results in lowering IGF Binding Protein 1 (IGFBP-1) levels and increasing the bioactive concentrations of IGF1." (PMID 40430851, 2025). "Hyperinsulinemia reduces hepatic synthesis of IGFBP-1 and IGFBP-2, thereby indirectly enhancing this signaling pathway and activating multiple classical oncogenic pathways, ultimately accelerating breast cancer progression." (PMID 41310487, 2025). "The derived network revealed a direct inverse effect of basal hyperinsulinemia on Insulin-like Growth Factor Binding Protein-1 (IGFBP-1), which then positively affects IGFBP2." (PMID 40502600, 2025). "Hyperinsulinemia suppresses hepatic insulin-like growth factor binding protein-1 synthesis, increasing bioavailable IGF-1, which in turn acts synergistically with LH to enhance ovarian androgen production." (PMID 41384021, 2025). "VAT induces hyperinsulinemia by the secretion of IGFBP1 and 2, increases free insulin and IGF-1, stimulates cell proliferation, inhibits apoptosis, and favors angiogenesis." (PMID 38785834, 2024). "When IGFBP-1 levels are low (in case of hyperinsulinemia), IGF-I bioactivity and IGF-I-mediated effects increase and supplement the actions of insulin." (PMID 36901984, 2023). "Hyperinsulinemia leads to reduced concentrations of insulin-like growth factor binding protein-1 (IGFBP-1) and glycodelin in the early stages of pregnancy, thereby interfering with the proliferation of trophoblasts." (PMID 35242105, 2022). "Low fasting serum IGFBP-1 levels reflect portal hyperinsulinemia even before peripheral hyperinsulinemia is detected." (PMID 35586622, 2022). "Along with the activation of IGF-1 receptor, hyperinsulinemia reduces the production of insulin-like growth factor-binding protein-1 (IGFBP-1) by ovarian granulosa cells." (PMID 33429918, 2021). "A study in T2D patients suggested that decreased IGFBP-1 concentrations were due to hyperinsulinemia." (PMID 33905470, 2020). "Circulating IGFBP-1, which is produced mainly by the liver, is normally suppressed in postprandial state by hyperinsulinemia and increased glycolysis." (PMID 32492897, 2020).
Hyperinsulinemia (continued). "Patients with type 1 diabetes have higher serum IGFBP‐1 concentrations than normoglycemic controls, and acute steady state hyperinsulinemia lowers serum IGFBP‐1 levels by 40–70% in normal individuals." (PMID 26443692, 2016). "IGFBP-1 is regulated at transcriptional level by insulin and low fasting levels are a marker of hyperinsulinemia." (PMID 25461385, 2014). "Chronic hyperinsulinemia inhibits the production of IGF-binding protein 1 (IGFBP-1) and IGFBP-2, which results in the increased bioavailability of IGF-1." (PMID 25402501, 2014). "Although IGFBP-1 levels in simple obesity are appropriately low for the prevailing hyperinsulinemia, in patients with obesity due to the Prader-Willi syndrome, IGFBP-1 concentrations are not suppressed." (PMID 24555152, 2013). "These opposite effects on IGFBP-1 production (insulin-independent stimulation versus insulin-dependent inhibition) observed in vitro, contrast with in vivo data showing that TZDs increase of IGFBP-1 synthesis, presumably because they reduce hyperinsulinemia." (PMID 19609453, 2009). "Thus, the relationship between insulin and IGFBP-I is inverse, where IGFBP-1 is low during states of hyperinsulinemia but elevated during states of hypoinsulinemia." (PMID 39665021, 2024). "However, when IGFBP-1 levels are chronically lowered during prolonged intra-portal hyperinsulinemia (e.g., obesity, Cushing’s syndrome and glucocorticoid therapy), the “accelerator” effect of IGFBP-1 is at play to increase serum free IGF-I." (PMID 39665021, 2024). "Postprandial hyperinsulinemia results in the suppression of Insulin-Like Growth Factor Binding Protein-1 (IGFBP-1), thereby increasing free IGF-1.Under conditions of caloric restriction, mammals produce less IGF-1, and its synthesis in the liver becomes refractory to GH stimulation." (PMID 39578883, 2024). "Reduced SHBG and IGF, preferentially insulin-like growth factor-binding protein 1 (IGFBP-1, also known as placental protein 12 or PP12), have been reported to be associated with hyperinsulinemia and represented as critical biomarkers/indicators of the metabolic syndrome." (PMID 37108615, 2023). "Moreover, overexpression of IGFBP1, a modulator of IGF1 action, is associated with hepatic ER stress, hyperinsulinemia and glucose intolerance." (PMID 37789023, 2023). "Hyperinsulinemia induces a decrease in insulin-like growth factor binding protein-1 and 2 (IGFBP-1 and 2) and reduces sex hormone binding globulin (SHBG) levels, resulting in an increase in free estrogen and androgen and insulin-like growth factor-1 (IGF-1) levels." (PMID 36755926, 2023). "Additionally, contrast to previous findings that insulin significantly suppresses IGFBP-1, our results suggested that the suppression of PCOS-related hyperinsulinemia on IGFBP-1 seemed diminished." (PMID 38174331, 2023). "Previous studies have shown a correlation between low levels of IGFBP-1 and hyperinsulinemia." (PMID 37762544, 2023). "Hyperinsulinemia not only reduces the levels of IGFBP-1 but also induces the production of IGF-1." (PMID 36474704, 2022). "As hyperinsulinemia decreases IGF-binding protein–1 (IGFBP-1) and IGFBP-2 levels, insulin may reduce certain IGFBP levels and increase bioavailable IGF levels to indirectly enhance the IGF–IGF-1R signaling pathway." (PMID 36213272, 2022). "The blood IGFBP-1 levels in PCOS women are significantly lower compare to than in healthy women, which may indicate suppression of IGFBP-1 production under the conditions of hyperinsulinemia." (PMID 33429918, 2021). "A reduction in concentrations of IGFBP-1 in hyperinsulinemia condition might stem from higher bioavailability of the free IGF-1, as well as the decreased levels of total IGF-1 and IGFBP-3." (PMID 31601230, 2019). "It implies that these finding may be due to hyperinsulinemia that could result in a decrease in the level of IGFBP-1." (PMID 31601230, 2019).